PRKCQ (protein kinase C theta)
Description:
Calcium-independent, phospholipid- and diacylglycerol (DAG)- dependent serine/threonine-protein kinase that mediates non-redundant functions in T-cell receptor (TCR) signaling, including T-cells activation, proliferation, differentiation and survival, by mediating activation of multiple transcription factors such as NF-kappa-B, JUN, NFATC1 and NFATC2. In TCR-CD3/CD28-co-stimulated T-cells, is required for the activation of NF-kappa-B and JUN, which in turn are essential for IL2 production, and participates in the calcium-dependent NFATC1 and NFATC2 transactivation. Mediates the activation of the canonical NF-kappa-B pathway (NFKB1) by direct phosphorylation of CARD11 on several serine residues, inducing CARD11 association with lipid rafts and recruitment of the BCL10-MALT1 complex, which then activates IKK complex, resulting in nuclear translocation and activation of NFKB1. May also play an indirect role in activation of the non-canonical NF-kappa-B (NFKB2) pathway. In the signaling pathway leading to JUN activation, acts by phosphorylating the mediator STK39/SPAK and may not act through MAP kinases signaling. Plays a critical role in TCR/CD28-induced NFATC1 and NFATC2 transactivation by participating in the regulation of reduced inositol 1,4,5-trisphosphate generation and intracellular calcium mobilization. After costimulation of T-cells through CD28 can phosphorylate CBLB and is required for the ubiquitination and subsequent degradation of CBLB, which is a prerequisite for the activation of TCR. During T-cells differentiation, plays an important role in the development of T-helper 2 (Th2) cells following immune and inflammatory responses, and, in the development of inflammatory autoimmune diseases, is necessary for the activation of IL17-producing Th17 cells. May play a minor role in Th1 response. Upon TCR stimulation, mediates T-cell protective survival signal by phosphorylating BAD, thus protecting T-cells from BAD-induced apoptosis, and by up-regulating BCL-X(L)/BCL2L1 levels through NF-kappa-B and JUN pathways. In platelets, regulates signal transduction downstream of the ITGA2B, CD36/GP4, F2R/PAR1 and F2RL3/PAR4 receptors, playing a positive role in 'outside-in' signaling and granule secretion signal transduction. May relay signals from the activated ITGA2B receptor by regulating the uncoupling of WASP and WIPF1, thereby permitting the regulation of actin filament nucleation and branching activity of the Arp2/3 complex. May mediate inhibitory effects of free fatty acids on insulin signaling by phosphorylating IRS1, which in turn blocks IRS1 tyrosine phosphorylation and downstream activation of the PI3K/AKT pathway. Phosphorylates MSN (moesin) in the presence of phosphatidylglycerol or phosphatidylinositol. Phosphorylates PDPK1 at 'Ser-504' and 'Ser-532' and negatively regulates its ability to phosphorylate PKB/AKT1. Phosphorylates CCDC88A/GIV and inhibits its guanine nucleotide exchange factor activity. Phosphorylates and activates LRRK1, which phosphorylates RAB proteins involved in intracellular trafficking.
Synonyms: PRKCT; nPKC-theta
Tractability: Small molecule: an approved drug acts on it; a structure with a bound ligand is known; a high-quality ligand is known; it has a binding pocket of medium quality; it belongs to a druggable protein family. Antibody: its Gene Ontology location is reachable by antibodies, with high confidence; UniProt places it where antibodies can reach, with medium confidence. PROTAC: ubiquitination databases record sites on it; its protein half-life has been measured; a small molecule that binds it is known.
Target class: AGC protein kinase group; Kinase; Enzyme; AGC protein kinase PKC delta subfamily; AGC protein kinase PKC family; Protein Kinase
Safety:
Unwanted effects reported when the protein is acted on. In parentheses: how it was acted on, where the effect was seen, and who reports it.
cardiac arrhythmia (cardiovascular system; source: Lamore et al. (2017))
Gene: Protein-coding gene on chromosome 10 (6,427,136 to 6,580,855, reverse strand). Ensembl gene ENSG00000065675.
Subcellular location: Cytoplasm; Cell membrane
Subcellular location (Human Protein Atlas): Centriolar satellite
Pathways (Reactome):
Immune System: Downstream TCR signaling; FCERI mediated NF-kB activation
Signal Transduction: G alpha (z) signalling events; RAS processing
Developmental Biology: Netrin-1 signaling
Gene expression (Transcription): RUNX1 regulates genes involved in megakaryocyte differentiation and platelet function
Hemostasis: Effects of PIP2 hydrolysis
Programmed Cell Death: Apoptotic cleavage of cellular proteins
Sensory Perception: Inactivation, recovery and regulation of the phototransduction cascade
Gene Ontology:
Molecular function: diacylglycerol-dependent, calcium-independent serine/threonine kinase activity; protein binding; protein kinase activity; protein serine kinase activity; protein serine/threonine kinase activity; ATP binding; diacylglycerol-dependent serine/threonine kinase activity
Biological process: cell chemotaxis; negative regulation of insulin receptor signaling pathway; negative regulation of T cell apoptotic process; positive regulation of telomere maintenance; axon guidance; Fc-epsilon receptor signaling pathway; intracellular signal transduction; membrane protein ectodomain proteolysis; positive regulation of interleukin-17 production; positive regulation of interleukin-4 production; positive regulation of T cell activation; positive regulation of T-helper 17 type immune response; positive regulation of T-helper 2 cell activation; regulation of cell growth; regulation of DNA-templated transcription; regulation of platelet aggregation; negative regulation of apoptotic process; positive regulation of DNA metabolic process; signal transduction
Cellular component: centriolar satellite; cytosol; plasma membrane; cytoplasm; immunological synapse
Genetic constraint (gnomAD): Loss-of-function variants: 41 observed, 93.1 expected, observed/expected ratio (o/e) 0.44, 90% interval 0.34 to 0.57. The upper end of that interval is the gene's LOEUF score, 0.57, which puts it in group 2 of 6, group 1 being the genes least tolerant of losing a copy. Missense variants: 661 observed, 931.15 expected, observed/expected ratio (o/e) 0.71, 90% interval 0.67 to 0.76. Synonymous variants: 298 observed, 328.16 expected, observed/expected ratio (o/e) 0.91, 90% interval 0.82 to 1.
Homologues: Orthologues: chimpanzee PRKCQ (99% identical), macaque PRKCQ (99% identical), dog PRKCQ (97% identical), pig PRKCQ (96% identical), guinea pig PRKCQ (95% identical), mouse Prkcq (95% identical), rat Prkcq (94% identical), rabbit PRKCQ (92% identical), zebrafish prkcq (75% identical), tropical clawed frog prkcq (74% identical). Paralogues in human: PRKCD (62% identical), AKT1 (28% identical), AKT3 (27% identical), AKT2 (27% identical), PDPK1 (19% identical).
Diseases named in the same sentence as PRKCQ in open-access papers:
PRKCQ is named in the same sentence as 58 diseases in open-access papers, as found by Europe PMC text mining. Sharing a sentence is not in itself a finding about the gene and the disease. The quoted sentences say what the papers report.
breast carcinoma (13 papers, 2012 to 2026). "We first identified PRKCQ as a candidate regulator of anchorage-independent survival of breast cancer cells in a functional kinome screen." (PMID 32600444, 2020). "PRKCQ expression directly suppresses the expression of ERα in breast cancer cells and is required for c-rel-induced mammary tumorigenesis." (PMID 32600444, 2020). "PRKCQ also stimulates breast cancer cell migration by stabilizing the expression of Fra-1 in TNBC cells." (PMID 32600444, 2020). "PRKCQ promotes breast cancer progression by enhancing the transcriptional activity via phosphorylation of the AP-1 transcription factor, Fra-1." (PMID 31626592, 2019). "The role of PRKCQ/PKCθ in the proliferation and survival of breast cancer cells and the responsible mechanisms, including dependency on kinase activity, remain to be clarified." (PMID 27663795, 2016). "PRKCQ also stimulates breast cancer cell migration by stabilizing the expression of Fra-1 in TBNC cells." (PMID 27663795, 2016). "In fact, PRKCQ expression directly suppresses the expression of ERα in breast cancer cells and is required for c-rel-induced mammary tumorigenesis." (PMID 27663795, 2016). "We first identified protein tyrosine kinase C theta isoform (PRKCQ)/PKCθ as a candidate regulator of anchorage-independent survival of breast cancer cells in a functional kinome screen." (PMID 27663795, 2016). "The kinase dependency of PRKCQ oncogenic activity supports the evaluation of these inhibitors in the context of breast cancer models." (PMID 27663795, 2016). "For breast cancer, of the six predicted candidates (PRKCQ, ARAF, MAPK14, BRMS1, CDC42BPA, SP3), three (PRKCQ, ARAF, MAPK14) are members of at least one KEGG cancer relevant pathway." (PMID 25961669, 2015). "PRKCQ could promote anoikis resistance via kinase-activity-dependent stimulation of Erk/MAPK in breast cancer." (PMID 38663918, 2024). "PRKCQ is a member of the novel protein kinase C (PKC) family and has been associated with many types of cancers, such as chromophobe renal cell carcinomas, breast cancer, and Notch-driven T-cell leukemia." (PMID 35846146, 2022). "Previous studies have shown that over-expression of PRKCQ, a member of the novel PKC family significantly enhances growth, migration and drug resistance of breast cancer cells; furthermore, silencing of PRKCQ inhibits breast cancer cell growth by promoting apoptosis." (PMID 31626592, 2019). "In addition, PRKCH is involved in drug resistance and regulation of apoptosis in breast cancer and PRKCQ promotes epithelial to mesenchymal transition (EMT) in breast cancer stem cells." (PMID 27144431, 2016). "Furthermore, PRKCQ may contribute to the formation or maintenance of a breast cancer stem cell population by promoting the expression of genes associated with epithelial-mesenchymal transition (EMT) through direct chromatin interactions." (PMID 27663795, 2016). "PRKCQ can also facilitate the growth of triple-negative breast cancer (TNBC) cells in vitro and in vivo, directly inhibiting ER expression in breast cancer cells." (PMID 37266435, 2023). "PRKCQ is reported to be expressed in solid tumors including gastrointestinal stromal tumors (GIST) and more recently, in breast cancer, specifically ER-negative tumors." (PMID 27663795, 2016). "Protein tyrosine kinase C theta isoform (PRKCQ)/PKCθ, a member of the novel PKC family, may have a distinct isoform-specific role in breast cancer." (PMID 27663795, 2016). "PRKCQ is expressed or activated in a subset of GIST, uveal melanoma, and breast cancers." (PMID 27663795, 2016). "By stabilizing Fra-1 expression, PRKCQ can also stimulate the migration of TNBC cells while promoting the epithelial-mesenchymal transition in these breast tumor cells through the phosphorylation and activation of LSD1, thus supporting breast cancer growth and dissemination." (PMID 37266435, 2023).
breast carcinoma (continued). "Finally, PRKCQ also promotes epithelial-mesenchymal transition of breast cancer cells by direct phosphorylation and activation of LSD1, which provides another mechanism by which PRKCQ promotes growth and spread of breast cancer." (PMID 32600444, 2020). "Protein kinase c theta (PRKCQ)/protein kinase C theta (PKCθ), as a member of the novel protein kinase C (PKC) family, was a regulatory factor that does not depend on adherence to survival in breast cancer cells, and was preferentially expressed in TNBC." (PMID 35414025, 2022).
autoimmune disease (8 papers, 2010 to 2024). A disorder resulting from loss of function or tissue destruction of an organ or multiple organs, arising from humoral or cellular immune responses of the individual to their own tissue constituents. "Dysregulation of PRKCQ activity has been linked to autoimmune diseases, inflammatory disorders, insulin resistance, type 2 diabetes, and the proliferation, migration, and invasion of cancer cells." (PMID 39234237, 2024). "In contrast, PRKCQ appears to be required for immune responses associated with autoimmune diseases and allograft rejection, perhaps due to a specific requirement for PRKCQ in the maturation of Th17 cells, a subset of CD4+ T cells." (PMID 32600444, 2020). "Based on the important roles that REL and PRKCQ genes play in the pathology of autoimmune diseases, the association between polymorphisms in the REL and PRKCQ genes and BD was investigated." (PMID 26784953, 2016). "Genome-wide association studies (GWAS) and candidate gene studies have identified the REL and PRKCQ genes as risk loci for various autoimmune diseases." (PMID 26784953, 2016). "Interestingly, PRKCQ is specifically required for the maturation and development of Th17 cells, which have been implicated in autoimmune diseases, such as multiple sclerosis and arthritis." (PMID 27663795, 2016). "A-1411735 is a protein kinase C theta (PKCθ) inhibitor that was evaluated as a potential treatment for autoimmune diseases." (PMID 33693348, 2019). "Data from the current study extend that of previous work identifying that CTLA-4, the IL2_21 region, 6q23 (TNFAIP3), SH2B3, PRKCQ, MMEL1 and now TAGAP are susceptibility loci that are common to the three autoimmune diseases examined in the current study: T1D, CeD and RA." (PMID 20854658, 2010).
Insulin resistance (6 papers, 2016 to 2026). Increased resistance towards insulin, that is, diminished effectiveness of insulin in reducing blood glucose levels. "For example, protein kinase C theta activation elicits vasoconstriction and has been shown to be associated with obesity and insulin resistance; the protein kinase C theta-mediated vasoconstriction occurs through a complex series of events, including Akt inhibition and ERK1/2." (PMID 27595112, 2016). "Another early study showed that PRKCQ knockout mice exhibited reduced energy expenditure and physical activity, leading to significantly increased adiposity and severe systemic insulin resistance when challenged with a high-fat diet." (PMID 41596924, 2026). "The samples from the carotid sheath showed an enriched expression of genes described to play a role in insulin resistance (PPP1R3E, PRKCQ, PRKCZ, CPT1B, MGEA5, RPS6KB2, OGT; KEGG_PATHWAY hsa04931:Insulin resistance)." (PMID 32661330, 2020). "In addition, for circFAT3 KD, genes related to insulin signaling and insulin resistance (PPARGC1A, SLC27A2, PPARGC1B, PRKCQ, GYS1, and IRS1) were the top hits." (PMID 36840844, 2023). "Knockdown of protein kinase C theta in the ARC or toll-like receptor 4 (TLR4)-adaptor molecule, MyD88, in the CNS prevented HFD- or ICV palmitate-induced weight gain and insulin resistance, highlighting some of the mechanisms of palmitate-induced central insulin resistance." (PMID 34831343, 2021).
asthma (4 papers, 2020 to 2024). "The asthma L-GRN includes HLA genes and other genes previously reported to be associated with asthma (e.g., PRKCQ, GSDMA, and GSDMB)." (PMID 37680636, 2023).
breast tumor (4 papers, 2016 to 2026). "PRKCQ is widely expressed in the entire hematopoietic system and can induce the production and migration of breast tumors." (PMID 36171883, 2022). "We examined the level and pattern of expression of PRKCQ in patients’ breast tumors." (PMID 27663795, 2016).
triple-negative breast carcinoma (4 papers, 2016 to 2023). An invasive breast carcinoma which is negative for expression of estrogen receptor (ER), progesterone receptor (PR), and human epidermal growth factor receptor 2 (HER2). "Higher PRKCQ/PKCθ expression can promote growth-factor-independent growth, anoikis resistance, and migration in triple-negative breast cancer cells." (PMID 33902604, 2021). "Protein kinase C theta, (PRKCQ/PKCθ) is a serine/threonine kinase that is highly expressed in a subset of triple-negative breast cancers (TNBC) and promotes their growth, anoikis resistance, epithelial-mesenchymal transition (EMT), and invasion." (PMID 32600444, 2020). "PRKCQ protein is not only sufficient to drive these phenotypes but is required for growth in vitro and in vivo of triple-negative breast cancer cells in which it is expressed." (PMID 32600444, 2020). "PRKCQ overexpression is also sufficient to enhance the viability of these cells in the presence of chemotherapeutic agents commonly used in the treatment of patient triple-negative breast cancers, such as doxorubicin and paclitaxel." (PMID 32600444, 2020).
angioedema (3 papers, 2020 to 2025). Swelling involving the deep dermis, subcutaneous, or submucosal tissues, representing localized edema. "According to GWAS, PRKCQ variation is associated with a lower incidence of angioedema." (PMID 40640196, 2025). "Variants in immune-regulating genes (ETV6) and protein kinase C (PRKCQ) are risk factors for the side effects of ACEI, including angioedema." (PMID 40640196, 2025). "We also found SNPs located close to the genes PRKCQ (protein kinase C theta), RAD51B (RAD51 Paralog B), and RIMS1 (regulating synaptic membrane exocytosis 1), which have previously been linked with drug-induced angioedema." (PMID 41189626, 2025). "In the candidate gene analysis, ETV6, BDKRB2, MME, and PRKCQ were nominally associated with angioedema (p < 0.05), but did not pass Bonferroni correction for multiple testing (p < 2.89 × 10−5)." (PMID 32080354, 2020). "ETV6, BDKRB2, MME, and PRKCQ were nominally associated with angioedema (p < 0.05), but none of the candidate genes was significantly associated after correction with multiple testing (p < 2.89 × 10−5)." (PMID 32080354, 2020). "The main findings were a non-significant association between risk of angioedema and the ETS Variant Transcription Factor 6 gene (ETV6) in African Americans, while a variant of the Protein Kinase C Theta gene (PRKCQ) tended to be protective in European Americans." (PMID 32080354, 2020).
Crohn disease (3 papers, 2022 to 2023). A gastrointestinal disorder characterized by chronic inflammation involving all layers of the intestinal wall, noncaseating granulomas affecting the intestinal wall and regional lymph nodes, and transmural fibrosis. "The TCONS_00072725 cis-acting target gene PKCƟ (encoded by PRKCQ) played a key role in regulating the differentiation and proliferation of T lymphocytes, and its mutation can cause the occurrence of Crohn’s disease and other diseases." (PMID 36672927, 2023). "Another study showed that missense mutations in PRKCQ are associated with Crohn's disease." (PMID 35346284, 2022).
chromophobe renal cell carcinoma (2 papers, 2019 to 2022). Chromophobe renal cell carcinoma is a rare subtype of renal cell carcinoma, originating from the intercalating cells of the collecting ducts and macroscopically manifesting as a well-circumscribed, highly lobulated, solid tumor that is usually diagnosed at an early stage. "In contrast, PRKCQ is significantly down-regulated in ccRCC and chromophobe renal cell carcinomas (ChRCCs)." (PMID 31626592, 2019).
glioma (2 papers, 2020 to 2024). A benign or malignant brain and spinal cord tumor that arises from glial cells (astrocytes, oligodendrocytes, ependymal cells). "Subsequent qPCR validation confirmed a significant increase in mRNA levels of CD30, PRKCQ, and ADAM8 in glioma cell lines (A172, U87MG, and PDX-L14) overexpressing FOSL1, which are key regulators at the apex of the NF-κB signaling pathway." (PMID 38856747, 2024).